PTH (parathyroid hormone)
Diseases named in the same sentence as PTH in open-access papers (continued):
Sharing a sentence is not in itself a finding about the gene and the disease.
Hypocalcemia (continued). "We found that PTH levels had a better correlation than calcium levels with the symptoms and signs of hypocalcaemia, and there was only a moderate correlation between POD 1 PTH and calcium levels." (PMID 39649119, 2024). "In mice, administration of LPS induced hypocalcemia and hyperphosphatemia, resulting in increased PTH and consequent renal expression of CYP27b1 and increased 1,25-dihydroxyvitamin D3." (PMID 38672379, 2024). "The removal or damage to parathyroid glands results in decreased secretion of PTH, leading to hypocalcemia and hyperphosphatemia." (PMID 39258042, 2024). "This highlights the importance of planning for back-up therapies (ie, administration of PTH subcutaneous injections or oral calcium and active vitamin D or having a new pod and medication available) to prevent hypocalcemia in case of pod failure." (PMID 38562130, 2024). "The algorithm is primarily based on the pathogenesis of hypocalcemia and hypophosphatemia; serum concentrations of calcium, phosphate, and PTH represent the key biochemical parameters to differentiate hypocalcemic from hypophosphatemic form of rickets." (PMID 38706696, 2024). "This mass was resected resulting in a fall in intraoperative PTH values and subsequent postoperative hypocalcemia secondary to hungry bone syndrome." (PMID 39611185, 2024). "The concentration of calcium in the blood is regulated by parathyroid hormone (PTH) and 1,25-dihydroxyvitamin D3, produced in response to hypocalcemia to increase blood calcium levels." (PMID 38473200, 2024). "Receiver operating characteristics curve analysis was performed to assess the PTH cutoff that better predicts POD 1 hypocalcaemia." (PMID 39649119, 2024). "Hypocalcemia and higher PTH are well-described phenomena in abdominal surgeries and are not specific to unilateral nephrectomies." (PMID 39462348, 2024). "Hypoparathyroidism was defined by the European Society of Endocrinology (ESE) as “a disease with hypocalcaemia and inappropriately low parathyroid hormone (PTH) levels”." (PMID 39636417, 2024). "One crucial complication of CKD is secondary hyperparathyroidism (SHPT), marked by elevated parathyroid hormone levels due to hyperphosphataemia, hypocalcaemia, and low active vitamin D from impaired renal function." (PMID 39208984, 2024). "In the group with PTH >10 pg/mL, the decrease in 1,25(OH)2D was a significant factor for Ca concentrations and hypocalcemia." (PMID 38803480, 2024). "We ruled out pseudohypoparathyroidism due to resistance to the action of parathyroid hormone with hypocalcemia, hyperphosphatemia, and elevated PTH levels, whereas our patient exhibited a low PTH level." (PMID 38905413, 2024). "The measurement of intact PTH levels post-surgery provides a valuable insight towards transient hypocalcemia (15-45 pg/ml)." (PMID 39290937, 2024). "In cases with positive clinical symptoms and signs of hypocalcemia and/or calcium levels <8 mg/dl, PTH level was measured before starting calcium infusion, while serum calcium and phosphorus levels were also measured 24 hours later." (PMID 38259695, 2024). "Hypoparathyroidism is characterized by hypocalcemia, elevated serum phosphate, and low or inappropriately normal PTH levels." (PMID 39328612, 2024). "During hypocalcaemia, parathyroid hormone (PTH) was measured in only 12 patients with 11 having normal or low PTH, confirming a diagnosis of hypoparathyroidism." (PMID 38308768, 2024). "Parathyroid hormone, serum, and ionized calcium were sampled post-surgery, with the presence of symptomatic or laboratory-verified asymptomatic hypocalcemia designated as primary outcome measures." (PMID 38322433, 2024). "It is characterized by congenital hypoparathyroidism with hypocalcemia, hyperphosphatemia, and severely reduced PTH levels, which represents a common manifestation of the syndrome." (PMID 39246904, 2024).
Hypocalcemia (continued). "Two weeks after denosumab administration, routine biochemical tests revealed severe hypocalcemia (serum calcium 6.2 mg/dl (1.55 mmol/L), with normal serum albumin levels and secondary hyperparathyroidism (PTH 332 pg/ml)." (PMID 39639476, 2024). "During hypocalcemia, CaSR is inactivated, which stimulates PTH secretion and subsequently the synthesis of calcitriol in the kidneys by the enzyme 1α-hydroxylase, regulated by the CYP27B1 gene." (PMID 38613476, 2024). "Given the persistence of hypocalcemia, a repeat PTH level was obtained which remained high at 487 pg/mL, suggesting ongoing PTH interference in the setting of COVID-19." (PMID 39355148, 2024). "Postoperatively, serum calcium and magnesium levels, PTH levels, and complications like hypocalcemia and hypomagnesemia were monitored." (PMID 39290937, 2024). "The best predictor for identifying hypoparathyroidism is the PTH level monitoring and serum calcium levels, and the early recognition of hypocalcemia-related symptoms is mandatory for prompt treatment and reduced hospital stay." (PMID 39457684, 2024). "During the 16-month follow-up, the patient’s PTH level decreased to 554 pg/mL, with slight fluctuations due to hypocalcemia." (PMID 38893652, 2024). "Hypocalcemia at diagnosis was present in 47% of the cases, hyperphosphatemia in 42%, and an elevated PTH at diagnosis in 64% of the cases." (PMID 39456695, 2024). "Hypocalcemia and hypophosphatemia are common during malarial infections, that can be attributed to low Vitamin-D3 and parathyroid hormone, but higher calcitonin in malaria patients." (PMID 39492784, 2024). "If the biochemical picture of hypocalcemia, hyperphosphatemia, and elevated PTH persists after vitamin D repletion, PHP is the likely diagnosis." (PMID 39350885, 2024). "Hypocalcemia is also known to stimulate the Ca and P intestinal absorption through the inhibition of the CaSR, leading to increased PTH secretion." (PMID 38613476, 2024). "Initial workup showed hypocalcemia, along with hypophosphatemia, with high 25(OH)-vitamin D levels, and elevated intact PTH (iPTH)." (PMID 39351120, 2024). "Short-term outcomes, including rates of postoperative hypocalcemia and parathyroid dysfunction, serum calcium and PTH levels on the first postoperative day, as well as the need for calcium supplementation, were analyzed." (PMID 38483607, 2024). "Several studies indicate that early postoperative PTH is the most accurate predictor of the development of symptomatic hypocalcemia after total thyroidectomy, but differing cut-off values and hypocalcemia criteria complicate the direct comparison of data." (PMID 38322433, 2024). "Pseudohypoparathyroidism is a rare disorder characterized by end-organ resistance to intact parathyroid hormone (PTH) and concomitant laboratory findings of hypocalcemia and hyperphosphatemia." (PMID 38435924, 2024). "Hypoparathyrodism is a rare endocrine disorder characterized by absence or inappropriately low levels of parathyroid hormone leading to hypocalcemia and hyperphosphatemia." (PMID 38481445, 2024). "In advanced CKD, hypocalcaemia and CaSR desensitisation due to gland hyperplasia increase PTH expression and secretion." (PMID 39208984, 2024). "Overall, patients with postoperative hypocalcemia had 65.7% lower PTH levels compared to preoperative levels, and this difference was highly evident in patients with postoperative PTH levels < 12 pg/mL (90.1%)." (PMID 36902740, 2023). "Magnesium is influenced, though to a lesser degree, by the same factors that control calcium, and it indirectly influences calcium by altering PTH synthesis and secretion in response to hypocalcemia and by assisting in the activation of vitamin D." (PMID 37007781, 2023). "The same homozygous S1-to-P1 change was subsequently identified in a third, unrelated patient with early-onset hypocalcemia and elevated PTH levels." (PMID 36795755, 2023).
Hypocalcemia (continued). "Pseudohypoparathyroidism (PHP) is defined as target organ resistance to parathyroid hormone (PTH), which results in hypocalcemia and hyperphosphatemia." (PMID 36123043, 2023). "It aimed at surveying the serum level of preoperative Vitamin D, PTH and calcium before total-thyroidectomy surgery and its relationship with the incidence of postoperative hypocalcemia after the surgery." (PMID 37636752, 2023). "Several studies have looked for predictive factors hypocalcemia or the need for post thyroidectomy Ca replacement, however most are based on falls in Ca and PTH absolute values and percentages between the pre and postoperative period." (PMID 36651710, 2023). "They found that on the second day after birth, Gnasxlm+/p- mice exhibited hyperphosphatemia, hypocalcemia, and increased serum PTH and 1,25-dihydroxy vitamin D concentrations." (PMID 37920253, 2023). "Pseudohypoparathyroidism type 1 (PHP1) is a rare disease featuring hypocalcemia and elevated PTH level." (PMID 38017461, 2023). "Routine blood tests showed severe anemia, increasing blood urea nitrogen and creatinine, elevated parathyroid hormone, hypocalcemia, hypokalemia and metabolic acidosis." (PMID 37993833, 2023). "Concomitant relative hypocalcemia can trigger PTH production and, consequently, 1.25(OH)2D production by the kidney." (PMID 38133239, 2023). "Biochemically, patients display hypocalcemia and hyperphosphatemia with normal or low parathyroid hormone (PTH) levels." (PMID 36980146, 2023). "Vitamin D catabolism is, instead, mutually regulated, as 24,25(OH)D production is stimulated by 1,25(OH)D itself, and is inhibited by hypocalcemia and PTH." (PMID 37761831, 2023). "Initial laboratory investigations showed hypocalcemia with normal magnesium and phosphate levels, while his parathyroid hormone levels were low." (PMID 38022014, 2023). "Given the challenges of cross-referencing PTH tests, the relative reduction between pre- and postoperative PTH levels has been suggested as a suitable adjunct to predict postsurgical hypocalcemia." (PMID 38030913, 2023). "Chronic hypoPT is defined by hypocalcaemia with inappropriately normal or low parathyroid hormone for more than six months." (PMID 37450218, 2023). "In contrast to HPT, PTH resistance is the hallmark of PHP, defined by elevated serum levels of PTH beyond hypocalcemia and hyperphosphatemia." (PMID 37854194, 2023). "During the last years, new treatment options like synthetic PTH analog (PTH 1-34) and human recombinant parathormone (PTH 1-84) have been introduced for patients whose hypocalcemia cannot be treated with the standard treatment." (PMID 37450218, 2023). "Temporary postoperative hypocalcemia developed in 147 patients (64%) in the group with PTH levels < 12 pg/mL compared to 84 patients (16.7%, p < 0.001) in the group with PTH levels > 12 pg/mL." (PMID 36902740, 2023). "This hypocalcemia then activates the parathyroid gland, leading to excessive secretion of parathyroid hormone (PTH) (secondary hyperparathyroidism; SHPT) to increase serum calcium levels again." (PMID 35511337, 2023). "The disorder develops as a result of inadequate activation of Vit D at the level of proximal tubule cells and subsequent hypocalcemia and hyperphosphatemia, which stimulate the secretion of PTH." (PMID 37432214, 2023). "Blood tests showed significantly elevated parathyroid hormone (PTH) (1073.00 pg/ml), hypocalcemia (0.49 mmol/L), hypokalemia (2.99 mmol/L), and metabolic acidosis." (PMID 37993833, 2023). "This significant reduction in conventional therapy was accompanied by a lower incidence of laboratory‐measured hypocalcemia in those receiving TransCon PTH." (PMID 36271471, 2023). "The primary hypoparathyroidism manifests as low serum concentrations of parathyroid hormone (PTH) leading to symptomatic or asymptomatic hypocalcemia." (PMID 37600721, 2023).
Hypocalcemia (continued). "Three patients from two unrelated families who presented during infancy with symptomatic hypocalcemia were found to have a homozygous serine (S) to proline (P) change affecting the first amino acid of the mature PTH." (PMID 36795755, 2023). "On 3 months follow up, 9(36%) patients who had low PTH and 1(2.9%) had persistent biochemical hypocalcemia." (PMID 37636752, 2023). "In patients with cirrhosis, hypocalcemia is prevalent due to reduced intake, poor absorption, low Alb, decreased parathyroid hormone, and reduced vitamin D levels." (PMID 37034104, 2023). "The patient reported by El Kawkgi developed hypocalcemia with low PTH levels during ipilimumab plus nivolumab treatment, but CaSR autoantibodies have not been measured." (PMID 36672478, 2023). "In this study, the patient was misdiagnosed until he presented with weight loss, severe anemia, mild proteinuria, elevated parathyroid hormone (PTH), hypocalcemia, hypokalemia, and metabolic acidosis secondary to ESKD at the age of 11." (PMID 37993833, 2023). "Hypoparathyroidism (hypoPT) is a rare endocrine disorder defined by hypocalcemia with inappropriately normal or low parathyroid hormone levels." (PMID 37380916, 2023). "Pseudohypoparathyroidism (PHP) includes a constellation of disorders that share biochemical characteristics of HPT (i.e., hypocalcemia and hyperphosphatemia), as a result of proximal tubular resistance to parathyroid hormone (PTH)." (PMID 37854194, 2023). "Pseudohypoparathyroidism (PHP), characterized by parathyroid hormone (PTH)-resistance or PTH-unresponsiveness at target organs, is associated with Fahr syndrome and typically presents with hypocalcemia." (PMID 38045865, 2023). "Symptomatic hypocalcaemia accompanied by low levels of parathyroid hormone (PTH) has been described in several case reports." (PMID 36884258, 2023). "In case of hypocalcemia (calcium < 8 mg/dL) with normal PTH the patient can be treated with calcium carbonate at a variable dosage from 2 to 6 g per day, in at least three administrations, or the equivalent of Calcium citrate." (PMID 37198359, 2023). "Postoperative and intraoperative serum-PTH has been analysed in various studies to predict hypocalcemia in post-total thyroidectomy." (PMID 37636752, 2023). "The increase of serum PTH in response to hypocalcemia is established; however, PTH levels are known to correlate positively with Pi intake and serum Pi levels in rodents and humans." (PMID 37079375, 2023). "A diagnosis of hypoparathyroidism is confirmed if PTH level is low to inappropriately normal in the setting of hypocalcemia." (PMID 37251665, 2023). "This partly opposes the current view in which the aggravating effect of low Mg2+ concentration on hypocalcemia is explained solely by the inhibition of Ca2+ mobilization due to interference with PTH secretion or signaling to osteoclasts." (PMID 37240030, 2023). "The genotype differences in PHP variants reflect a heterogeneity of phenotypes that generally share the biochemical features of hypoparathyroidism, namely hypocalcemia and hyperphosphatemia, but with an unexpected elevation of serum PTH." (PMID 38137593, 2023). "After increased synthesis and secretion of PTH by multiple stimuli (hypocalcemia, hyperphosphatemia, decreased calcitriol, etc.), PTH binds to its receptors in bone tissue (mostly PTHR1), which are located on the surface of OBs and osteocytes." (PMID 37342799, 2023). "Hypocalcemia increases PTH levels (secondary hyperparathyroidism), resulting in increased bone resorption of calcium, thereby causing soft tissue mineralization and bone de-mineralization." (PMID 36827665, 2023). "In fact, parathyroid gland injury can lead to a decrease in parathyroid hormone, and patients will have symptoms such as perioral numbness and hypocalcemia convulsions." (PMID 37334307, 2023).
Hypocalcemia (continued). "In aspects of hormones, glucocorticoids pose an impact on calcium excretion and absorption, promoting hypocalcemia, with secondary increased parathyroid hormone (PTH), ending in increased bone resorption." (PMID 36982891, 2023). "No research on the correlation between cigarette smoking and hypocalcemia was found, previous studies seem to focus mainly on the correlation between smoking and PTH, and the conclusions were inconsistent." (PMID 36597085, 2023). "Although low Mg levels stimulate PTH secretion, Mg is also required for the production and release of PTH and therefore severe hypomagnesemia can lead to clinical hypocalcemia via hypoparathyroidism." (PMID 36771254, 2023). "Freire demonstrated that PTH assay ≤14 pg/ml 60 min postoperatively had a sensitivity of 90% and specificity of 100% in predicting hypocalcemia." (PMID 37215594, 2023). "Mg2+ deficiency is known to contribute to the development and severity of hypocalcemia, suggesting a link between hypocalcemia and parathyroid hormone (PTH) receptor signaling at low Mg2+ concentrations." (PMID 37240030, 2023). "PHP1B is characterized by end-organ resistance to several endocrine hormones, including parathyroid hormone (PTH) leading to hypocalcaemia and hyperphosphatemia, and thyroid stimulating hormone (TSH) leading to clinical or subclinical hypoparathyroidism." (PMID 37635873, 2023). "A different homozygous PTH1R mutation was recently identified in a child from a consanguineous family who exhibited delayed ossification, consistent with Eiken syndrome, but also marked PTH-resistance (hypocalcemia with elevated PTH)." (PMID 37268817, 2023). "Hyperphosphatemia and hypocalcemia along with low parathyroid hormone values supported the suspicion of primary hypoparathyroidism." (PMID 37456991, 2023). "Participants treated with TransCon PTH experienced lower rates of hypocalcemia during the trial compared with placebo." (PMID 36271471, 2023). "4-hours post-operative PTH measurements showed 51% sensitivity, 100% specificity and strong co-relation between postoperative hypocalcemia and drop in PTH levels- (p=<0.001)." (PMID 37636752, 2023). "With this in mind, the simulation results for hyperparathyroidism and hypocalcemia indicate that for the given pattern of glandular PTH secretion, a catabolic bone response is obtained." (PMID 36996072, 2023). "Meta-analyses of selected risk factors confirmed that the most significant factor in the incidence of hypocalcemia was a decrease in PTH levels (p < 0.001)." (PMID 37626794, 2023). "Despite optimization of surgical approach, postoperative hypocalcemia due to unopposed osteoblast uptake of minerals after acute decrease in PTH levels remains a common complication after parathyroidectomy in these patients and can lead to poor outcomes." (PMID 37606078, 2023). "New treatment options such as synthetic PTH analog (PTH 1–34) and human recombinant parathormone (PTH 1–84) are only available for those patients in whom hypocalcemia cannot be adequately treated with conventional treatment." (PMID 37380916, 2023). "Patients with end stage renal disease under dialysis (hemodialysis or peritoneal dialysis) have low levels of 1,25 (OH) 2 D3, which results in a decrease in calcium absorption which leads to hypocalcemia and a secondary increase in PTH secretion." (PMID 38075043, 2023). "Hypocalcemia due to Mg deficit, secondary to decreased PTH secretion or peripheral PTH resistance, is additionally deteriorated by a lack of the PTH stimulation of renal 1-alpha-hydroxylation, with the further worsening of vitamin D deficit." (PMID 36986033, 2023). "Pseudohypoparathyroidism (PHP) and nonsurgical hypoparathyroidism (NS-HypoPT) are rare diseases with hypocalcemia, hyperphosphatemia, and high and low parathyroid hormone levels, respectively." (PMID 36123043, 2023).